S100A3 (S100 calcium binding protein A3)
Description:
Binds both calcium and zinc. May be involved in calcium-dependent cuticle cell differentiation, hair shaft and hair cuticular barrier formation.
Synonyms: S100E
Tractability: Antibody: its Gene Ontology location is reachable by antibodies, with high confidence; the Human Protein Atlas places it where antibodies can reach.
Gene: Protein-coding gene on chromosome 1 (153,547,329 to 153,550,151, reverse strand). Ensembl gene ENSG00000188015.
Subcellular location: Cytoplasm
Subcellular location (Human Protein Atlas): Cytosol; Golgi apparatus; Plasma membrane
Gene Ontology:
Molecular function: protein binding; calcium ion binding; calcium-dependent protein binding; transition metal ion binding
Cellular component: cytosol; Golgi apparatus; plasma membrane; cytoplasm
Genetic constraint (gnomAD): Loss-of-function variants: 13 observed, 11.47 expected, observed/expected ratio (o/e) 1.13, 90% interval 0.74 to 1.74. The upper end of that interval is the gene's LOEUF score, 1.74, which puts it in group 6 of 6, group 1 being the genes least tolerant of losing a copy. Missense variants: 124 observed, 132.05 expected, observed/expected ratio (o/e) 0.94, 90% interval 0.81 to 1.09. Synonymous variants: 43 observed, 52.24 expected, observed/expected ratio (o/e) 0.82, 90% interval 0.64 to 1.06.
Homologues: Orthologues: chimpanzee S100A3 (100% identical), macaque S100A3 (98% identical), rabbit S100A3 (96% identical), mouse S100a3 (90% identical), rat S100a3 (90% identical), pig S100A3 (86% identical), guinea pig S100A3 (70% identical), zebrafish s100t (34% identical), zebrafish s100s (33% identical), zebrafish s100a10a (28% identical), tropical clawed frog s100a11 (20% identical). Paralogues in human: S100A4 (43% identical), S100A6 (41% identical), S100A2 (40% identical), S100A1 (39% identical), S100A5 (36% identical), S100B (36% identical), S100Z (35% identical), S100A9 (30% identical), S100P (30% identical), S100A12 (29% identical), S100A11 (27% identical), S100A13 (27% identical), and 9 more.